NEDD4 (NEDD4 E3 ubiquitin protein ligase)
Diseases named in the same sentence as NEDD4 in open-access papers (continued):
Sharing a sentence is not in itself a finding about the gene and the disease.
cancer (95 papers, 2012 to 2026). A tumor composed of atypical neoplastic, often pleomorphic cells that invade other tissues. "By interacting with these BC-associated pathways, NEDD4 proteins play important roles in BC tumorigenesis, cell proliferation, metastasis, ferroptosis, cancer stem cells (CSCs), and drug resistance." (PMID 40535763, 2025). "Cancer development and progression have been linked to the aberrant regulation of the NEDD4 protein." (PMID 37605223, 2023). "When its expression or activity is dysregulated, NEDD4-1 can cause protective autophagy in favor of the cancer cell requirement." (PMID 36918822, 2023). "The neuronally expressed developmentally downregulated 4 (NEDD4) gene encodes a ubiquitin ligase that targets the epithelial sodium channel for degradation and has been implicated in tumor growth in various cancers." (PMID 35031788, 2022). "Our studies have provided a new regulatory mechanism underlying the NEDD4-promoted cancer cell migration." (PMID 34833029, 2021). "These aberrations lead to malignant transformations, underlying the significance of NEDD4 in tumorigenesis and cancer development." (PMID 28423617, 2017). "In support of this notion, NEDD4 overexpression was observed to positively correlate with the loss of PTEN in human cancer." (PMID 24657926, 2014). "Dysregulation of Nedd4 activity has also been linked to disease pathogenesis outside of cancer." (PMID 37749144, 2023). "Furthermore, subsequent molecular experiments were performed to confirm our findings that NEDD4 were closely implicated in many biological processes of different cancers." (PMID 37291499, 2023). "Changes in the structure of the NEDD4 gene involved in a number of intracellular mechanisms of nucleartranslation of proteins, lysosomal and proteosomal degradation dramatically increase the risk of developing malignant neoplasms." (PMID 37372468, 2023). "NEDD4 has also been implicated in the development of other types of cancer." (PMID 35031788, 2022). "In addition, NEDD4 is also linked to several diseases, including cancer, cardiovascular disease, metabolic disease, neurological disorders, renal disease, and others." (PMID 36293239, 2022). "It has been demonstrated that SIRT2 inhibition by TM, a potent SIRT2-specific inhibitor with a broad anticancer effect in numerous human cancer cells as well as mouse models of BC, promotes expression of the NEDD4 E3 Ubiquitin Protein Ligase for c-Myc, causing c-Myc ubiquitination and degradation." (PMID 35406775, 2022). "Additionally, it was discovered that NEDD4 expression led to the total loss of gap junctions and an increase in the lysosomal degradation of Cx43 in HeLa cancer cells." (PMID 36293239, 2022). "NEDD4-1 likely acts as a novel drug target or diagnostic marker in the battle against cancer." (PMID 31787758, 2019). "Expression of NEDD4 was directly associated with cancer progression, particularly metastasis." (PMID 28423617, 2017). "The ubiquitin ligase NEDD4-1 plays an important role in organ development, tissue homeostasis, and cancer." (PMID 41488203, 2026). "Recurrent insertions were located near cancer-associated genes, including RB1, NEDD4, FTO, LAMA2, NOD1, and KCNB2, implicating LINE-1 activity in cis-regulatory remodeling of oncogenic pathways." (PMID 41681929, 2026). "Biomarker identification is another critical step to select cancer types reliant on NEDD4-1-mediated PTEN degradation, enabling better patient stratification for optimal therapeutic outcomes." (PMID 40002221, 2025). "Because there exist many target proteins for E3 ubiquitin ligase NEDD4, feasibility of NEDD4 intervention in anti‐cancer therapy is still needed further confirmation in the future." (PMID 41292194, 2025). "In this study, we also found that NEDD4 plays a cancer-promoting role in OXA-resistant cells by silencing NEDD4 (si-NEDD4), which is consistent with the findings of previous studies." (PMID 39890782, 2025).
cancer (continued). "Studies have shown that NEDD4 is dysregulated in various types of cancer, potentially promoting tumor development by affecting cell proliferation, apoptosis, metabolism, migration, and invasion." (PMID 38783226, 2024). "Its anti-cancer properties have been attributed at least in part to its inhibitory activity of proto-oncogenic HECT E3-ubiquitin ligases such as NEDD4 and WWP1." (PMID 39519210, 2024). "For example, NEDD4 is overexpressed in a number of cancers (e.g., breast, bladder, and colon cancer), where it can perform its oncogenic or oncostatic function by inducing the ubiquitination of PTEN, Myc, Ras, and other substrates." (PMID 38785984, 2024). "This is in line with a recent study that identified the E3 ubiquitin ligase NEDD4 as a key factor for PD-L1 degradation in FGFR3-activated cancer, providing a mechanistic link for potential drug combinations in the future." (PMID 38473263, 2024). "The ubiquitin E3 ligase NEDD4-1 has been found to involve in the proliferation, migration, invasion, and drug sensitivity of cancer cells." (PMID 36918822, 2023). "NEDD4 targets several proteins involved in cancer growth, including RAS, AKT, and phosphatase and tensin homolog (PTEN)." (PMID 36672488, 2023). "For example, ACLY is ubiquitinated and subsequently degraded by E3 ligase NEDD4 in lung cancer cells and is a key metabolic enzyme that produces the acetyl-CoA required for fatty acid metabolism in cancer." (PMID 37176148, 2023). "There is an ever-expanding list of oncogenic and tumor suppressor miRNAs, lncRNAs and circRNAs, which needs experimental and clinical assessment for the re-interpretation of diagnostic and prognostic markers in NEDD4-overexpressing or NEDD4-defective cancers." (PMID 37568787, 2023). "Overall, the use of NEDD4 activator compounds as well as tumor suppressor lncRNAs and circular RNAs will be helpful in the comprehensive characterization of strategies for cancer prevention." (PMID 37568787, 2023). "For instance, few studies reported NEDD4 as a tumour suppressor while others have reported NEDD4 to promote cancer growth." (PMID 38097550, 2023). "Growing evidence has shown that NEDD4-1 can also play the role in the autophagy process in cancer cells, thereby affecting tumor growth." (PMID 36918822, 2023). "Mounting evidence has demonstrated that NEDD4 participates in the tumorigenesis of human cancers, such as cervical cancer, hepatocellular carcinoma, and breast cancer." (PMID 37497216, 2023). "The NEDD4-1 can also involve in the phagophore elongation and substrate selection in cancer cells through interaction with LC3 and the autophagy receptor SQSTM1." (PMID 36918822, 2023). "NEDD4 is well known to initiate and promote cancer as it degrades tumor suppressor protein PTEN through poly-ubiquitination and dictates nuclear localization via mono-ubiquitination." (PMID 37176148, 2023). "This accumulating evidence suggested that E3 ligase NEDD4 is a potential target for cancer therapeutics." (PMID 38097550, 2023). "For elucidating the molecular significance exhibited by NEDD4 E3 ligase family genes in cancer, we analyzed the relation between NEDD4 E3 ligase family genes and pathways related to cancer." (PMID 37291499, 2023). "Currently, NEDD4 is suggested to be overexpressed in various cancers including CRC and malignant gastric cancer." (PMID 38097550, 2023). "Next, we analyzed the relation between NEDD4 E3 ligase family genes and pathways related to cancer in order to elucidate the molecular significance." (PMID 37291499, 2023). "Now that the crosstalk between autophagy and cancer metabolism is more fully appreciated, it can be assumed that NEDD4-mediated regulation of Beclin1 affects tumor progression by reprogramming cancer metabolism." (PMID 37176148, 2023). "Analysis of the nine NEDD4 E3 ligase family genes of TCGA data suggested that NEDD4 E3 ligase family genes were distributed heterogeneously in various cancer types." (PMID 37291499, 2023).
cancer (continued). "For many cancers like TGCT, PCPG, THCA and UVM, NEDD4 E3 ligase family genes seldom reported mutation." (PMID 37291499, 2023). "In this study, we analyzed the data of different cancers at various levels of DNA, RNA and proteins to generate the expression, copy number variation, protein interactions in relation to different NEDD4 members of tumor in detail." (PMID 37291499, 2023). "The involvement of NEDD4 in DNA damage and cancer metabolism makes it a promising target for cancer therapy." (PMID 37176148, 2023). "Our findings provide novel insight into the effect of NEDD4 E3 ligase genes on cancer progression and treatment in the future." (PMID 37291499, 2023). "The cox regression results showed the relation between NEDD4 E3 ligase family genes and the cancer prognosis." (PMID 37291499, 2023). "The immunohistochemistry results from the Protein Atlas database gave the protein expression regarding NEDD4 E3 ligase family genes of the 33 cancer types." (PMID 37291499, 2023). "In summary, our study systematically demonstrated the expression, mutation, copy number variation, functional pathways and prognostic value of NEDD4 E3 ligase family genes across multiple cancers." (PMID 37291499, 2023). "First, an overview of NEDD4 ubiquitin ligases as well as the autophagy process and its role in cancer cells were briefly presented in the following introduction subsections." (PMID 36918822, 2023). "Afterward, all published data regarding the role of NEDD4 ubiquitin E3 ligases in the autophagy process in cancer have been reviewed and discussed in detail." (PMID 36918822, 2023). "In conclusion, these studies have established that NEDD4 can affect proliferation in various cancer cells." (PMID 36293239, 2022). "In several studies, NEDD4 has been proven to promote tumor growth, and thus targeting this protein for cancer treatment is a promising method." (PMID 36293239, 2022). "Apart from these studies, the role of NEDD4 has also been studied in other cancers, such as multiple myeloma (MM), uveal melanoma, bone cancer, gall bladder cancer, etc.." (PMID 36293239, 2022). "In most cancer types, NEDD4 inhibits tumorigenesis by increasing the degradation of NEDD4 substrates which have a crucial oncogenic role in various malignancies; however, its significance in a few cancer types is still debated." (PMID 36293239, 2022). "In this review, to comprehend the proper function of NEDD4 in cancer development, we summarize its function, both its tumor-suppressive and oncogenic role, in multiple types of malignancies." (PMID 36293239, 2022). "A surfeit of studies has found that NEDD4 exhibits a potential oncogenic role and is frequently overexpressed in various types of cancers." (PMID 36293239, 2022). "A plethora of studies have shown that NEDD4 promotes tumor growth in diverse types of cancers, and these studies suggest that the role of NEDD4 in tumor progression is context-dependent." (PMID 36293239, 2022). "In several studies, it was reported that among the HECT family E3s, the function of NEDD4/NEDD4-like E3 ligases influences cancer cell proliferation, migration, and invasion, as well as anticancer therapy sensitivity, via regulating several substrates." (PMID 36293239, 2022). "Supporting findings were identified in a previous study, indicating the potential oncogenic role of NEDD4 and suggesting that NEDD4 is frequently overexpressed in a wide array of human cancers, such as prostate and bladder cancers." (PMID 35031788, 2022). "In the current article, we discuss the function of the NEDD4 protein in the development and suppression of cancer." (PMID 36293239, 2022). "NEDD4 has a significant role in the development and progression of various types of cancers by targeting different substrates." (PMID 36293239, 2022). "According to several studies, it was noted that NEDD4 overexpression increases cell migration and invasion in various cancers." (PMID 36293239, 2022).
cancer (continued). "A study demonstrated the relationship between NEDD4 and EC, in which the cancer tissues showed increased levels of NEDD4." (PMID 36293239, 2022). "Our case is the first report of a non‐SS malignant neoplasm identified in the literature to harbor the novel SS18::NEDD4 fusion gene." (PMID 35639915, 2022). "Mechanistically, the dichotomous function of NEDD4 in human cancers is centered on its indiscriminate ability to recognize the PPR motifs which are widespread motifs in proteins with diverse functions." (PMID 33962630, 2021). "Recently, NEDD4 has been reported to play either oncogenic or suppressive roles in multiple human cancers." (PMID 33767993, 2021). "NEDD4 is known to regulate cell proliferation, cell migration, and tumorigenesis in various cancer types." (PMID 33962630, 2021). "NEDD4 has been demonstrated to negatively regulate the PTEN protein levels in numerous cancers, such as prostate, bladder, lung, and colon." (PMID 34298639, 2021). "NEDD4 is a HECT‐type E3 ligases which induces ubiquitination of tumor suppressive proteins to elicit oncogenic functions in diverse cancers." (PMID 34586722, 2021). "NEDD4 is a key regulator of IGPR-1 expression with implication in the therapeutic targeting of IGPR-1 in human cancers." (PMID 33962630, 2021). "The expression and the molecular function of NEDD4 have frequently been studied in various human cancers." (PMID 33014839, 2020). "NEDD4 plays a critical role in diverse cellular functions in cancers, including tumor initiation, progression, migration, and resistance to anticancer therapies." (PMID 33014839, 2020). "Evidence has revealed that NEDD4 plays a critical role in the development and progression of human cancer, including NSCLC." (PMID 33288736, 2020). "Although many signaling pathways regulated by NEDD4 in cancers have been discovered, the role of NEDD4 in CSCs remains elusive." (PMID 33014839, 2020). "Several groups have reported that multiple natural compounds inhibit the expression of NEDD4 in a variety of human cancers." (PMID 33288736, 2020). "Overexpression of Nedd4 facilitated tumor cell growth, whereas depletion of Nedd4 significantly inhibited the proliferation of cancer cells in vitro and tumor growth in vivo." (PMID 31974380, 2020). "Given the role of NEDD4 in cancer, NEDD4 is considered to be a promising therapeutic target for the treatment of human malignancies." (PMID 33014839, 2020). "Several studies have demonstrated that Nedd4 can act as an oncogene in promoting cancer cell growth." (PMID 31974380, 2020). "Overall, abnormal levels of Nedd4 appear to consistently exert oncogenic tendencies through various regulatory substrates across several human cancers." (PMID 31974380, 2020). "The expression of NEDD4 is frequently upregulated in several human cancers and positively correlated with cell proliferation and survival via ubiquitination-mediated proteosomal degradation of tumor suppressors, such as PTEN, and LATS." (PMID 33014839, 2020). "Despite accumulated findings pointing to tumor-promoting functions, the roles of NEDD4 in cancer appear to be more complex." (PMID 31856858, 2019). "This review discusses the role of the multifunctional NEDD4-1 protein in human cancer biology and the mode by which NEDD4-1 regulates each substrate." (PMID 31787758, 2019). "NEDD4-1 has a large number of upstream and downstream genes, and its dual role in cancer makes it a possible molecular switch to regulate tumor development through these competitive substrates." (PMID 31787758, 2019). "While NEDD4 functions as an oncogene in most cancers, it can also act as a tumor suppressor in some tumors." (PMID 31856858, 2019). "NEDD4 can distinctly regulate degradative ubiquitination of different types of protein substrates in various cancer models, which leads to the promotion or suppression of tumorigenesis." (PMID 31856858, 2019).
cancer (continued). "In the next section, we introduce the substrates of NEDD4-1 and the possible application of NEDD4-1 in cancer therapeutics in detail." (PMID 31787758, 2019). "As such, both increased and decreased levels of NEDD4 are observed in different types of human cancer, making it likely that NEDD4’s role in tumorigenesis is variable depending on the context." (PMID 31905981, 2019). "Overexpression of NEDD4 has been reported in several cancer types and downregulation of NEDD4 appears to reduce proliferation, migration and invasion of cancer cells." (PMID 31001145, 2019). "Our study is the first to systemically compare NEDD4 expression in BC tissue at different stages of cancer progression." (PMID 31856858, 2019). "Given the role of NEDD4 in cancer growth, progression, and its poor prognosis, NEDD4 as a target is considered to be a promising therapeutic strategy for the treatment of human malignancies." (PMID 31856858, 2019). "To determine the role of NEDD4 in cancer cell migration in vitro, we conducted wound healing and transwell assays." (PMID 31856858, 2019). "Numbers of research reports have observed that NEDD4 regulates cancer cell proliferation through ubiquitination and down-regulation of the tumor suppressor PTEN, which is an inhibitor of the PI3K/AKT pathway." (PMID 29455656, 2018). "It seems that NEDD4 can distinctly regulate degradative ubiquitination of those different types of protein substrates in various cancer models, which leads to promotion or suppression of tumorigenesis." (PMID 29851245, 2018). "In addition, many other abnormalities related to vesicular transport have been observed as hallmark of cancer and malignant transformation, such as altered casitas B-lineage lymphoma (Cbl) and neural precursor cell-expressed developmentally down-regulated protein 4 (Nedd4)." (PMID 31105241, 2018). "On the other hand, it has been demonstrated that NEDD4 mediates ubiquitination and degradation of various cancer‐related proteins." (PMID 29851245, 2018). "Overall, these results suggest that proteasomal degradation of PIP5Kα by NEDD4 can be an alternative way for controlling the protein and PIP2 levels leading to suppression of PI3K/Akt‐associated cancer progression." (PMID 29851245, 2018). "The majority (87.4%, 104 of 119) of carcinomas showing high membranous HER3 expression were demonstrated to co-overexpress NEDD4–1 protein." (PMID 30367623, 2018). "Our study provides evidence that glucose-mediated signalling, consisting of NEDD4-mediated H3 ubiquitination and subsequent Gcn5-mediated H3 acetylation, plays important roles in maintaining such population of cancer cells." (PMID 28300060, 2017). "Together, our study reveals the mechanism for glucose-induced transcriptome reprograming and epigenetic regulation in cancer by inducing NEDD4-dependent H3 ubiquitination." (PMID 28300060, 2017). "Together, these studies reveal an important role of glucose-induced H3 ubiquitination by NEDD4 in cancer development." (PMID 28300060, 2017). "To evaluate the clinical relevance of this finding, we analysed the The Cancer Genome Atlas (TCGA) exon expression data sets for NEDD4 and top-ranked genes in cancer-related pathways from microarray." (PMID 28300060, 2017). "Amounting evidence has revealed that NEDD4 is frequently overexpressed in a range of human cancers which suggests that NEDD4 is a legitimate target for designing new drugs to treat human malignancies." (PMID 27042197, 2016). "Biologically, NEDD4-1 overexpression sensitizes cancer cells to etoposide-induced apoptosis by reducing SAG levels through targeted degradation." (PMID 25216516, 2014). "PTEN is known to be a substrate of the UPS in cancer cell lines via various E3 ubiquitin ligases, including Nedd4." (PMID 24349488, 2013). "NEDD4 is highly expressed in the skin, skeletal muscle, the liver, the bladder, placenta and cancer cell lines." (PMID 23667473, 2013).